LYZ (lysozyme)
Diseases named in the same sentence as LYZ in open-access papers (continued):
Sharing a sentence is not in itself a finding about the gene and the disease.
amyloidosis (continued). "In addition to diverse partners that interfere with Aβ fibrillization, amyloidosis of amylin is affected by 7B2, proSAAS, lysozyme, and alpha-lactalbumin." (PMID 33708792, 2020). "Clearly, the question whether SAP possesses a beneficial or an adverse effect in lysozyme amyloidosis and in other amyloid diseases require further investigations." (PMID 31978114, 2020). "A better understanding of the process of amyloidogenesis for lysozyme could yield insights into treatments for many different types of amyloidoses." (PMID 30029603, 2018). "We hypothesized that these residues may facilitate an interprotein interaction between native state amyloidogenic lysozyme proteins, contributing to the first steps of amyloidosis." (PMID 30029603, 2018). "Thus these studies conclude that PVP-coated gold nanoparticles act as effective inhibitory and disaggregating agents against HEWL amyloids and thus can serve as potential therapeutics against lysozyme amyloidosis." (PMID 28536362, 2017). "However, several mutations in the gene encoding the protein, including Y54N, I56T, F57I, W64R, D67H and T70N/D112H (in humans) give rise to lysozyme amyloidosis." (PMID 27428539, 2016). "There are clear indications that SAP may play an important role in lysozyme amyloidosis, which requires further elucidation." (PMID 27428539, 2016). "Herein, we present the case of a U.S. family affected by lysozyme amyloidosis." (PMID 29043133, 2015). "We have investigated fibril formation by hen egg white lysozyme, an enzyme for which human variants underlie non-neuropathic amyloidosis." (PMID 21483680, 2011). "Misfolding of transthyretin (meningovascular amyloidosis), angiotensinogen, β2 – microglobulin, lysozyme, the Notch3 gene product, and the familial prion protein may each lead to amyloidosis." (PMID 16321154, 2005). "Amyloid aggregation of human lysozyme is responsible for lysozyme amyloidosis, a non-neuropathic hereditary amyloidosis in which protein mutations favor the formation of misfolded conformers which in turn leads to lysozyme aggregation and accumulation of amyloid deposits in several organs." (PMID 34205510, 2021). "On the other hand, if the toxicity in lysozyme amyloidosis is due to the massive accumulation of amyloid aggregates in internal organs, the presence of SAP could potentially promote the formation of these amyloid species and thereby worsen the disease progression." (PMID 31978114, 2020). "Furthermore, it provides insight into lysozyme amyloid formation that may be applicable to the study of many other amyloidoses." (PMID 30029603, 2018). "To improve understanding of the processes involved we expressed human wild type (WT) lysozyme and the disease-associated variant F57I in the central nervous system (CNS) of a Drosophila melanogaster model of lysozyme amyloidosis, with and without co-expression of serum amyloid p component (SAP)." (PMID 27428539, 2016). "Thus, there are clear indications that SAP may play an important role in lysozyme amyloidosis that requires further elucidation." (PMID 27428539, 2016). "The amounts of Apo E and lysozyme proteins frequently exceeded the minimal amounts of IGK and IGL in ALκ and ALλ amyloidosis, respectively." (PMID 32609750, 2020). "We have also recently reported the use of UV-denaturation assay to probe the mechanism of amyloidosis of α-synuclein, glial fibrillary protein (GFAP), and human lysozyme." (PMID 30065161, 2018). "Aggregation of lysozyme into amyloid fibrils can give riseto hereditary non-neuropathic lysozyme amyloidosis." (PMID 40369858, 2025). "The IR marker bands of abnormal protein aggregation have been determined for β2-microglobulin (β2m), whose deposits occurred in dialysis-related amyloidosis within the musculoskeletal system, a prion-forming 218–289 domain of HET protein, wild-type human lysozyme and hen egg white lysozyme (HEWL)." (PMID 32471300, 2020).
amyloidosis (continued). "As there is no radical therapy for lysozyme amyloidosis, patients were given symptomatic treatment such as antihypertensive drugs and antibiotics." (PMID 31395023, 2019). "Lysozyme amyloidosis has no known effective treatment and leads to lysozyme amyloid deposits typically concentrated in the liver, spleen, gastrointestinal tract, and kidneys." (PMID 30029603, 2018). "In addition, while the histopathological appearance of the amyloid-forming CAs and spheroid-type amyloid deposits were nearly identical, the latter deposition lacked β2-microglobulin and lysozyme and exhibited evident destruction of the surrounding tissue." (PMID 38612850, 2024). "In the case of human cystatin C, the decrease in strand along with an increase in helix might have prevented amyloidosis, despite the fact that helix change was not always as evident as in the case of lysozyme." (PMID 15904486, 2005).
colitis (36 papers, 2015 to 2025). Inflammation of the colon. "Overall, our data indicate that loss of Nod2 signaling in lysozyme-expressing myeloid cells lowers carcinogenesis in the context of colitis." (PMID 37876927, 2023). "To determine if Nod2 plays an intrinsic role in the extravasation of these lysozyme-expressing CD102+ peritoneal macrophages to the colon in DSS-mediated colitis, we made Nod2-deficient competitive bone marrow (BM) chimeras (as described recently)." (PMID 37876927, 2023). "Microbes from these three genera have been associated with inflammatory bowel disease, colitis, and hemorrhagic diarrhea; thus, lysozyme activity could play some role in mitigating levels within these three genera." (PMID 38191395, 2024). "Loss of Nod2 signaling in myeloid cells contributes to tissue repair in the inflamed large intestine through lysozyme secretion by myeloid cells, which may explain the lower incidence of colitis in Crohn’s disease patients with NOD2 mutations." (PMID 37876927, 2023). "Similarly, Lee and colleagues reported that mice fed a HFD had decreased Paneth cells, reduced lysozyme release, and disruption of intestinal barrier function and were more susceptible to experimentally induced colitis." (PMID 33055426, 2020). "This aligns with clinical observations—fecal lysozyme levels correlate positively with inflammation severity in Crohn’s disease patients, and Paneth cell-derived lysozyme can worsen colitis." (PMID 41374020, 2025). "Given that the pathogenesis of IBD is driven by pathogenic immune responses to gut microbiota, we analyzed the intestinal microbiota using the T-RFLP method to evaluate the mitigating effects of ESM and its major component LYZ in a DSS-induced colitis model." (PMID 41009682, 2025). "This action helps to alleviate colon damage and mucosal inflammation in mice with colitis, indicating that lysozyme plays a significant role in modulating the microbial community." (PMID 39766345, 2024). "Loss or gain of function in intestinal lysozyme in mice dampened or exacerbated dextran sulfate sodium-induced colitis, suggesting that proper control of the abundance of intestinal luminal lysozyme is important for inflammatory disease progression." (PMID 38823640, 2024). "Other studies revealed that lysozyme attenuates the dextran sulfate sodium (DSS)-induced colitis by modulating the gut microbiota, increasing the relative abundance of Akkermansia muciniphila." (PMID 39766345, 2024). "In line with this, other authors have shown that lysozyme significantly reduced the expression of IL-17 in dextran sodium sulfate-induced colitis." (PMID 38673881, 2024). "In Pan’s cell-specific lysozyme knockout (Lyz1) mice, transplanting Ruminococcus_gnavus can induce type 2 immune response, skin reprogramming, and enhance the anti-colitis ability." (PMID 36674937, 2023). "Then, colitis is more severe in Per1/2 KO mice than in WT mice, with decreased Paneth cells, goblet cells, lysozyme transcripts, and lysozyme proteins." (PMID 38089624, 2023). "Fungal lysozyme appears capable of leveraging the gut microbiota to dose-dependently alleviate experimental colitis." (PMID 35291443, 2022). "Depletion of the commensal microbiota by broad-spectrum antibiotics abrogated lysozyme efficacy, pointing toward microbiota-dependency in the lysozyme mediated protection against DSS-induced colitis." (PMID 34693864, 2021). "Observed improvements of intestinal health relied on a complex gut flora, with the observation that microbiota depletion abrogated lysozyme’s capacity to mitigate DSS-induced colitis." (PMID 34693864, 2021). "We next sought to investigate the role played by the intestinal microbiota in the promotion of lysozyme-mediated protection against DSS-induced colitis." (PMID 34693864, 2021).
colitis (continued). "To further evaluate the efficacy of intestinal inflammation, we next supplemented chow-fed BALB/c mice with lysozyme during Dextran Sulfate Sodium (DSS)-induced colitis in either conventional or microbiota-depleted mice." (PMID 34693864, 2021). "To further investigate the beneficial outcome of lysozyme supplementation on intestinal health, we assessed colon damage in chemically induced mild colitis." (PMID 34693864, 2021). "We aimed here to improve bowel function in diet-induced obesity and chemically induced colitis through daily oral administration of lysozyme, a well-characterized HDP, derived from Acremonium alcalophilum." (PMID 34693864, 2021). "Levels of lysozyme are elevated in many diseases characterized by gut hyperpermeability including celiac disease, colitis, and Crohn's disease, suggesting that microbial flora upregulates this enzyme." (PMID 31019506, 2019). "In a colitis porcine model, lysozyme was demonstrated to significantly protect animals from colitis and reduce the local expression of pro-inflammatory cytokines while increasing the expression of the anti-inflammatory mediators." (PMID 30909449, 2019). "At baseline and after the recovery phase of DSS colitis, Tfebflox/flox animals had similar numbers of lysozyme+ Paneth cells in the ileum, as evidenced by anti-lysozyme staining." (PMID 29066772, 2017). "The study showed that intestinal epithelial VDR deletion impaired antimicrobial function of Paneth cells by downregulation of Atg16l1 and lysozyme, thus causing increased susceptibility to DSS-induced colitis." (PMID 28119697, 2016). "Mechanistically, NFAT5 promoted the survival of IECs and the renewal of intestinal stem cells, thereby regulating the production of mucus and antimicrobial compounds, including RegIII and lysozyme, which consequently shape the gut microbial composition to prevent colitis." (PMID 40663408, 2025). "Therefore, supplementation with lysozyme derived from hen egg attenuated the severity of colitis induced by DSS and improved nutrient absorption." (PMID 37876927, 2023). "While LYZ has been associated with colitis, and S100P associated with the progression of colitis-associated dysplasia, neither LYZ nor NPSR1 had been shown to be associated with CAC." (PMID 29983891, 2018). "Further, we have extended these findings and confirmed the presence of these signatures at the protein level in CAC organoids and tissues, demonstrating increased expression of LYZ and S100P in both colitis and CAC, and increased expression of NPSR1 in colitic organoids and tissues." (PMID 29983891, 2018). "Furthermore, global knockout of Atg4b caused alterations in Paneth cell, including less number and small size of granules and decreased lysozyme, and Atg4b-deficient mice were more susceptible to DSS-induced colitis." (PMID 28119697, 2016). "A previous report regarding the use of another AMP, fungal lysozyme, showed that in an experimental colitis model the presence of gut microbiota was required for the therapeutic effects of the treatment, suggesting that the effects of hBD-2 may similarly be microbiota-dependent." (PMID 35153819, 2021). "In the present study, the use of the LysMcre knock-in/knock-out mice led us to unveil that specific ablation of Nod2 expression in myeloid cells renders mice more resistant to colitis and CAC in a lysozyme-dependent manner." (PMID 37876927, 2023). "Ectopic Lyz1 production in colonic epithelium was able to suppress lysozyme-sensitive bacteria such as R. gnavus ATCC 29149 and exacerbated colitis." (PMID 37015876, 2023). "Furthermore, lysozyme supplementation could ameliorate intestinal inflammation in porcine colitis." (PMID 35491818, 2022). "Our results further exhibited a stronger staining of lysozyme and LGR-5 in the gut epithelial crypt of patients with colitis too." (PMID 26687459, 2015).
colitis (continued). "In experimental colitis and graft versus host disease (GVHD) mice, the researchers found that programmed cell death ligand 1 (PD-L1) maintains the intrinsic function of Foxp3 by specifically lowering the AEP in lysozyme." (PMID 36609651, 2023). "Interestingly, another scRNA-seq analysis revealed that LYZ, a Paneth cell marker, was upregulated in lower-crypt goblet cells and might mark the “deep crypt secretory cells” that are required to maintain the colonic stem cell niche and to protect stem cells from bacterial damage during colitis." (PMID 36045190, 2022). "Moreover, daily lysozyme gavage conferred strong protection against DSS-induced colon shortening and spleen weight, as well as both macro- and microscopic colitis scores." (PMID 34693864, 2021). "Encouraged by the observed benefits of lysozyme administration in the obesity setting primarily targeting the large intestine, we next evaluated the efficacy of a short-term DSS-challenged mouse model of mild colitis." (PMID 34693864, 2021). "Taken together, our data suggests that blocking IL-4/IL-13 signalling specifically on lysozyme M-positive macrophages and neutrophils has no significant influence in the onset of colitis." (PMID 32410852, 2020). "Likewise, significantly reduced numbers of secretory Paneth cells, goblet cells and lysozyme were detected in colitis-affected mice without Per1/2." (PMID 37218867, 2023). "In conclusion, A. alcalophilum-derived lysozyme administration reshaped the gut microbiota composition along with its predicted functions, diminished HFD-induced intestinal permeability and bacterial encroachment, as well as microbiota-dependently diminishing DSS-induced colitis." (PMID 34693864, 2021).
sarcoidosis (32 papers, 2012 to 2025). Sarcoidosis is a multisystemic disorder of unknown cause characterized by the formation of immune granulomas in involved organs. "Our findings showed that only triggering receptors expressed on myeloid cells 2–positive (TREM2-positive) macrophages (TREM2 macrophages) expressing angiotensin-converting enzyme (ACE) and lysozyme, diagnostic markers of sarcoidosis, were found to be increased in cutaneous sarcoidosis granulomas." (PMID 38038136, 2023). "We observed that the percentages of triggering receptor expressed on myeloid cells 2–positive (TREM2-positive) macrophages expressing angiotensin-converting enzyme (ACE) and lysozyme, diagnostic makers of sarcoidosis, were increased in cutaneous sarcoidosis granulomas." (PMID 38038136, 2023). "However, the specificity of serum lysozyme level has been reported to be less for sarcoidosis than serum ACE level, and it has been considered that the diagnostic value of serum lysozyme for sarcoidosis might be limited." (PMID 26879979, 2016). "Lysozyme can help in the diagnosis of sarcoidosis, as in our cohort, levels were more elevated in the sarcoidosis group (54% versus 12%)." (PMID 38787250, 2024). "When we classified patients according to disease etiology, higher SLPI levels were found in Sarcoidosis than in other etiologies, and levels of lysozyme were similar in all groups." (PMID 38673881, 2024). "They actually performed lysozyme staining in various cases of tubulointerstitial nephritis from different etiologies and only cases of sarcoidosis consistently showed positive for lysozyme." (PMID 38890580, 2024). "Elevated serum angiotensin-converting enzyme (ACE) and lysozyme have been suggested as tools for the diagnosis of sarcoidosis." (PMID 38787250, 2024). "Concerning labs results, lysozyme was measured in 87% of sarcoidosis patients (n = 111) and was elevated in 54% of the total sarcoidosis group (n = 69)." (PMID 38787250, 2024). "ACE (angiotensin-converting enzyme) and lysozyme levels were also determined, ruling out sarcoidosis, and HLA-B (human leukocyte antigen) was determined, confirming the presence of HLA B*07 and HLA B*15." (PMID 38592169, 2024). "The frequency of elevated lysozyme in sarcoidosis patients varies among the studies, 18,8% —79,1% and its level correlates with the number of organs involved." (PMID 37721575, 2023). "In one study, among 13 children with probable, presumed, or definite sarcoidosis 5 patients had elevated lysozyme levels." (PMID 37721575, 2023). "There was a significant difference (p = 7.7e−14) in the lysozyme levels between controls (median = 5 μg/mL) and sarcoidosis subjects (median = 21.1 μg/L)." (PMID 36207373, 2022). "Increased concentration of lysozyme is mainly observed at onset of disease and has low sensitivity for sarcoidosis." (PMID 32760396, 2020). "Increase in lysozyme concentration in body fluids is also regarded as an early warning of some diseases such as Alzheimer’s, sarcoidosis, Crohn’s disease, and breast cancer." (PMID 32050422, 2020). "In sarcoidosis, lysozyme is produced by monocyte-macrophage systems and epithelioid cells, and is involved in granuloma formation." (PMID 32760396, 2020). "Diagnostic finality based on serum and CSF testing was limited by the poor sensitivity of ACE and lysozyme in the diagnosis of sarcoid." (PMID 31010318, 2019). "Clinical disease activity has been correlated with serum ACE, lysozyme and sIL-2R in patients with sarcoidosis." (PMID 30154391, 2018). "According to this graph, the lowest value for the estimated marginal mean of serum lysozyme level was13.200 mg/L for control group, and the highest value was 20.776 mg/L for patients with presumed sarcoidosis." (PMID 26879979, 2016). "Our study revealed the estimated marginal means of serum lysozyme for patients with AS, BD, presumed sarcoidosis, presumed latent TB, presumed latent syphilis and control group as 14.124, 14.371, 20.765,14.987, 13.980, and 13.196 mg/L respectively." (PMID 26879979, 2016).